HIF1A (hypoxia inducible factor 1 subunit alpha)
Diseases named in the same sentence as HIF1A in open-access papers (continued):
Sharing a sentence is not in itself a finding about the gene and the disease.
prostate carcinoma (continued). "Thus, miR-34a-5p/HIF1A, miR-34a-5p/IGFBP2 and miR-34a-5p/PIK3CB, as well as Axl, could represent possible biomarkers and therapeutic targets for prostate cancer; conversely, miR-34a-5p upregulation is associated with the development of AD." (PMID 35741059, 2022). "Here, we proposed a hypothesis that TRPM7 might respond to hypoxia to regulate the degradation of HIF-1α, and thus to control its downstream target, Annexin A1, and subsequently to affect the hypoxia-induced aggressive ability of androgen-independent prostate cancer cells." (PMID 32215176, 2020). "Propofol reversed the drug resistance of docetaxel induced by hypoxia and attenuated the process of EMT via inhibition of HIF‐1α in prostate cancer cells, suggesting that propofol may help overcome prostate cancer's resistance to chemotherapy under hypoxic conditions." (PMID 32596964, 2020). "Furthermore, both TRPM7 and HIF-1α knockdown significantly suppressed hypoxia-induced Annexin A1 protein expression, and suppression of HIF-1α/Annexin A1 signaling significantly inhibited hypoxia-induced cell migration and invasion of androgen-independent prostate cancer cells." (PMID 32215176, 2020). "Therefore, we investigated whether PRKAR2B regulates HIF‐1α expression or activity in prostate cancer." (PMID 33025691, 2020). "Likewise, disruption of filamentous septin structures by FCF reduces the tumorigenic properties like proliferation, migration and transformation in prostate cancer cells via ubiquitination and degradation of HIF-1α protein, a process normally prevented by filamentous septin structures." (PMID 31857849, 2019). "We suspected that G allele of HIF-1α G1790A might be associated with low levels of HIF-1α and might be negative association of G allele with prostate cancer risk." (PMID 31419966, 2019). "Moreover, HIF-1α plays a role in prostate cancer cell EMT and migration." (PMID 29568752, 2018). "To investigate whether the decrease in HIF-1α expression by CA in hypoxic prostate cancer cells involves in the SPHK-1 pathway, AKT, and GSK-3β and to delineate the downstream signaling mechanism of SPHK-1, we performed western blot analysis and SPHK-1 activity assay." (PMID 28165392, 2017). "Moreover, our study found that atorvastatin could inhibit protein expression of HIF-1α in human prostate cancer in a dose-dependent manner, suggesting a potentially antitumor effect of statins in prostate cancer." (PMID 28760843, 2017). "Taken together, the present meta-analysis manifests that HIF1A rs11549465 polymorphism may not be an independent risk factor for prostate cancer." (PMID 28415653, 2017). "Based on the role of hypoxia-associated molecules in cancer cell biological behaviour and clinical outcome, we assumed there might be an association, at the genetic and protein level, between HIF1A, LOX, CA9 and KDR genetic variants, the protein expression and prostate carcinoma." (PMID 28143503, 2017). "Similarly, melatonin was found to downregulate HIF-1α synthesis in DU145 prostate cancer cells." (PMID 29207653, 2017). "Our findings indicate that HIF1A rs11549465 polymorphism may not independently play a significant role in the occurrence of prostate cancer." (PMID 28415653, 2017). "Indeed, soluble factors secreted by CAF induce in prostate cancer the oxidation and phosphorylation of PKM2 prompting the nuclear translocation of the enzyme and its association with HIF-1α and the differentially expressed in chondrocyte-1, a transcriptional repressor, which downregulates miR-205." (PMID 28352611, 2017). "Thus, we suppose that atorvastatin may inhibit prostate cancer cells and enhance radiosensitivity of prostate cancers cells through inhibiting HIF-1α." (PMID 28760843, 2017). "Thus, in this study, we evaluated whether the inhibition of HIF-1α by CA involves the SPHK-1 pathway under hypoxia in the DU145 human prostate cancer cell line." (PMID 28165392, 2017).
prostate carcinoma (continued). "Therefore, our study suggested that atovastatin could increase radiosensitivity in prostate cancer cells, especially hypoxia-induced prostate cancer cells, through inhibition of HIF-1α." (PMID 28760843, 2017). "Interestingly, it has been reported that HIF-1α may in turn stimulate mTOR signaling in prostate cancer stem cells leading to their resistance to selective mTOR inhibitors." (PMID 27821815, 2016). "Furthermore, we provide evidence that increased PHF8 expression in prostate cancer clinical samples correlates with the severity of tumor hypoxia (pre- vs post-castration) and elevated levels of HIF1α and HIF2α and Gleason grades, poor prognosis and lower overall survival." (PMID 27991916, 2016). "Recent findings suggest that HIF-1α may also increase prostate cancer chemoresistance." (PMID 27821815, 2016). "Indeed, our findings of non-hypoxic stabilization of HIF-1α suggest that it might be possible to develop a small molecule interfering with the ERβ2 and ERβ5-induced HIF-1α stabilization for use in therapy of certain aggressive forms of prostate cancer." (PMID 26010887, 2015). "In the context of concurrent deletions of KLF5 and PTEN in human prostate cancer, our findings further suggest that during the development of human prostate cancer, KLF5 loss and PTEN loss cooperate to enhance tumor angiogenesis by upregulating HIF1α and VEGF, which remains to be examined." (PMID 25896712, 2015). "Furthermore, we observed that overexpressing miR-182 could increase HIF1α expression and promote tumor angiogenesis in a prostate cancer xenograph model." (PMID 26205124, 2015). "Thus, further investigations into MAOA-mediated therapy resistance mechanisms should seek to determine if the primary effects of MAOA inhibition on prostate cancer treatment responses operate through HIF1α versus other ROS-dependent or ROS-independent pathways." (PMID 25198178, 2014). "Thus, ARRB1 acts a co-regulator of HIF1A activity in prostate cancer cells." (PMID 24837709, 2014). "In addition, artificial over-expression of miR199b in prostate cancer cells may significantly impair the HIF-1α expression under normoxic and hypoxia-mimicking conditions, together with reduced cell growth and increased cell apoptosis." (PMID 23594994, 2013). "In vitro studies of prostate cancer have shown that AKT, as an upstream regulatory hub, can directly stabilize and activate the expression and function of HIF-1α through the PI3K/AKT signaling pathway." (PMID 41368570, 2025). "This reciprocal relationship was similarly observed in two additional prostate cancer cell lines, PC3 and DU145, indicating that HIF1α-mediated suppression of FOXA1 is a broadly conserved response." (PMID 40643528, 2025). "In prostate cancer, FOXA1 co-occupies reprogrammed AR-binding sites and represses an intragenic enhancer within the HIF1A locus, implicating it in the modulation of hypoxic responses." (PMID 40643528, 2025). "Taken together, these findings establish HIF1α, PHD1, and PHD3 as positive regulators of prostate cancer cell proliferation and migration." (PMID 40643528, 2025). "Our initial observation that global PHD inhibition using DMOG led to HIF1α stabilization but paradoxically reduced FOXA1 protein levels prompted us to investigate whether individual PHD isoforms differentially regulate FOXA1 expression in prostate cancer cells." (PMID 40643528, 2025). "In prostate cancer cells, curcumin inhibited MAO-A/mTOR/HIF1α signaling, thus suppressing epithelial-mesenchymal transition, while a synthesized flavonoid derivative with MAO-A inhibiting properties displayed anti-proliferative and anti-metastatic activities." (PMID 39714760, 2025).
prostate carcinoma (continued). "To assess the functional consequences of HIF1α- and PHD-mediated regulation in prostate cancer, we evaluated their effects on cell proliferation and migration using LNCaP 1F5 and V16A cell lines." (PMID 40643528, 2025). "Because VEGF transcription largely relies on HIF‐1α in hypoxia, apigenin decreases VEGF expression which, in turn, decreases angiogenesis in prostate cancer." (PMID 40781971, 2025). "This study highlights the potential of SSA as a therapeutic agent for prostate cancer by identifying its key molecular targets (BCL2, ESR1, HIF1A, and STAT3) and validating its anti-proliferative and pro-apoptotic effects in PC3 cells." (PMID 39995416, 2025). "In prostate cancer, UBE2O expression is upregulated, negatively correlated with AMPKα2, and positively correlated with mTOR/HIF1α." (PMID 40426910, 2025). "HIF-1α lactylation promotes the transcription of KIAA1199, facilitating angiogenesis and advancing the progression of prostate cancer." (PMID 39325940, 2024). "We initially evaluated the presence of HIF-1α by immunoblot in the various cells, including P69 normal epithelial cells, DU145 and PC3 prostate cancer cells and 786-O kidney cancer cells." (PMID 38978018, 2024). "In prostate cancer, elevated lactate uptake via MCT1 results in the lactylation of HIF-1α, which allows it to maintain high stability in normoxic environments." (PMID 39325940, 2024). "This extract also decreased tumour size, vessel density, and the expression of HIF-1α and VEGF in prostate cancer xenografts in severe combined immunodeficient (SCID) mice, indicating its potential to inhibit tumour growth and angiogenesis in vivo." (PMID 39683144, 2024). "Subsequent to XHP treatment, the protein expression levels of HIF-1α, GLUT1, HK2, and PKM2 in both prostate cancer tissues and the two cell lines showed a significant reduction." (PMID 38994113, 2024). "Studies have shown that in HEK293 cell and prostate cancer disease models, HSP90 and receptor for activated C kinase (RACK1) can competitively bind HIF1A, and then inhibit proteasomal pathway degradation." (PMID 38385089, 2024). "Regarding the PI3K/Akt/mTOR pathway, the YC-1 drug has been found to inactivate this pathway by reducing the accumulation of HIF-1a and HIF-1b and antagonizing the activation of nuclear factor (NF-kB) induced by hypoxia in prostate cancer cells." (PMID 36787054, 2023). "The high expression of NPAS2 promotes the release of HIF-1A and key glycolytic genes (HK2, PKM2, GLUT1 and MCT4), enhancing glycolytic metabolite levels, thus inducing the progression of prostate cancer cells." (PMID 36978001, 2023). "Following that, we examined the correlation between HIF-1A and NPAS2 mRNA expression in prostate cancer tissues in the TCGA database." (PMID 36978001, 2023). "In addition, it suppressed apoptosis and accelerated cell growth in prostate cancer by hypoxia inducible factor-1,it is a transcription factor widely existing in mammals and human body under hypoxia conditions, and a key factor in response to hypoxia stress (HIF-1α) pathway." (PMID 36588796, 2022). "BCL9 possesses hypoxia-responsive elements in its promoter region, and hypoxia and HIF1α induce BCL9 expression in liver, colon, and prostate cancer cells." (PMID 35027586, 2022). "What’s more, both HIF-1α and PFKP expression were significantly reduced in prostate cancer received docetaxel treatment in vivo." (PMID 36536346, 2022). "In accordance with a study on kidney cancer, which showed that TGF-β increases HIF-1α and HIF-2α under normoxic conditions, a study on prostate cancer cell lines revealed that TGF-β induces HIF-1α, HIF-2α and VEGF production under normoxic conditions." (PMID 35625561, 2022). "Blocking the PDGF system by imatinib inhibits HIF-1α and IGF-I expression in prostate cancer cells and xenograft models." (PMID 35158804, 2022).
prostate carcinoma (continued). "A study has showed that TRPM8 over-expressed in advanced prostate cancer, and TRPM8 promoted cancer cell growth in vitro hypoxia, drug resistance, and in vivo tumorigenicity, with increased HIF-1α expression." (PMID 36033489, 2022). "BCL9 possesses hypoxia-response elements in its promoter region, and hypoxia and HIF1α induce BCL9 expression in liver, colon, and prostate cancer cells." (PMID 35027586, 2022). "Isoflurane was found to induce the upregulation of HIF-1α and enhancement of human renal cancer cell RCC4 and prostate cancer cell PC3 and ovarian cancer proliferation and migration." (PMID 35559987, 2022). "The gene expression data of prostate cancer (PRAD) patients in The Cancer Genome Atlas (TCGA) cohort suggested a moderate positive correlation (r = 0.22; p = 5.7 × 10−8) between HIF1A and CPT1A expression." (PMID 34944922, 2021). "TRPM7 silencing, however, significantly promoted hypoxia-inducible factor 1 alpha (HIF-1α) degradation through the proteasome and inhibited EMT changes in androgen-independent prostate cancer cells under hypoxic conditions." (PMID 33856653, 2021). "The hypoxia-induced radioresistance of prostate cancer cells (22Rv1 and DU145 cell lines) was connected with HIF-1α-mediated G2/M arrest and decreased apoptosis in the irradiated cells." (PMID 33806538, 2021). "The relationship of HIF-1α and VEGF-A with radio-therapy-induced intestinal damage in prostate cancer or CC were also evaluated." (PMID 33146980, 2021). "In prostate cancer, it has been reported that androgens acting through the PI3K/Akt pathway, in a transcription-independent fashion, increase HIF1α protein levels." (PMID 33784295, 2021). "Knockdown of TRPM7 significantly promoted HIF-1α degradation through the proteasome and inhibited EMT changes in androgen-independent prostate cancer cells under hypoxic condition." (PMID 32215176, 2020). "Although not investigated in this study, we have previously observed concomitant expression of HIF1-α and the chemotactic receptor, CXCR4, in DU145 prostate cancer cells under H2O2 oxidative stress." (PMID 32719369, 2020). "HIF-1α also directly regulates BCL-xL, which is a hypoxia-responsive, anti-apoptotic protein of the Bcl-2 family and is also overexpressed in prostate carcinoma and many other cancers." (PMID 32509575, 2020). "In prostate cancer, MAOA induced EMT and stabilized the expression of HIF-1α protein, ultimately promoting the growth, invasion, and metastasis." (PMID 32792865, 2020). "Recently, in prostate cancer, MAOA was reported to stabilize HIF-1α and mediate hypoxia by increasing ROS that can repress PHD activity, thereby enhancing the growth, invasion, and metastasis of prostate cancer cells." (PMID 32792865, 2020). "Using human DU145 prostate cancer cells, we assessed the effect of the NO mimetic glyceryl trinitrate (GTN) and the cGMP analogue 8-Bromo-cGMP on hypoxic accumulation of HIF-1α." (PMID 31912870, 2020). "Reduction of HIF-1α, as well as downregulation of TRPM7, inhibited EMT and invasion of prostate cancer cells." (PMID 32215176, 2020). "In prostate cancer, SNHG1 acts as an miR-199a sponge, thus increasing the level of CDK7 (cyclin-dependent kinase 7), which stimulates cell division, and HIF-1α (hypoxia-inducible factor 1-alpha), which leads to enhanced angiogenesis." (PMID 32318335, 2020). "In human prostate cancer PC3 cells, which have a detectable HIF-1α protein basal level under normoxia (20% O2), ALM dose-dependently reduced HIF-1α protein expression under both normoxic and hypoxic conditions." (PMID 31083403, 2019). "Correlation of HIF-1α, MDR1, and LAPTM4B expression with clinico-pathological features of prostate cancer." (PMID 30746305, 2019). "A similar pattern of linear correlation was also found among HIF-1α, MDR1 and LAPTM4B in case of prostate cancer (R = 0.806, p < 0.001) with 12 patients having high expression of these genes while six patients having low expression of these genes." (PMID 30746305, 2019).
prostate carcinoma (continued). "Summarizing our results, FGFR2 interacts with HIF-1α and HIF-2α, and represses their transcriptional activities in prostate cancer cells." (PMID 30837551, 2019). "Recently, dual targeting of HIF-1α and AR pathways by HIF-1α inhibitors and enzalutamide, a second generation AR inhibitor, showed synergistic effect in castration-resistant prostate cancer cell lines, also resulting in decreased VEGF-A levels." (PMID 31151317, 2019). "The expression of HIF-1α, MDR1 and LAPTM4B was studied in blood of 72 breast, 42 ovarian, 32 colon and 21 prostate cancer patients through real time PCR analysis using delta cycle threshold method." (PMID 30746305, 2019). "Recently we have shown that they bind to and stabilize HIF-1α and HIF-2α in prostate cancer cells, thus activating hypoxic signaling under normoxic conditions and in addition shown that they are recruited to HIF-1α response elements in chromatin." (PMID 30555629, 2018). "In the present study, we explored the effects of severe hypoxia on the crosstalk between HIF-1α and PKM2 in the context of prostate cancer." (PMID 30216369, 2018). "ERK and Akt activation enhances HIF-1α and VEGF expression in human malignant lung epithelial cells and prostate cancer cells." (PMID 29725496, 2018). "MSA have also been reported to inhibit HIF-1α expression and VEGF secretion in lymphoma cell lines and in prostate cancer cells." (PMID 30324091, 2018). "We have recently shown that they bind to and stabilize both HIF-1α and HIF-2α in prostate cancer cells, thus activating hypoxic signaling under normoxic conditions and furthermore are recruited to HIF-1α response elements in chromatin." (PMID 29552303, 2018). "CPE decreased the abundance of HIF-1α and sphingosine kinase-1 (SPHK-1) in hypoxia-induced prostate cancer DU145 cells." (PMID 28165392, 2017). "The genotypic distributions for the putative functional target SNPs in HIF1A, LOX, CA9 and KDR were similar between nodular prostate hyperplasia and prostate carcinomas." (PMID 28143503, 2017). "In prostate cancer EGF stimulates tumor progression via the coordinated ROS production, the phosphorylation of STAT3 (required for EGF-induced upregulation of HIF-1α) and the consequent induction of HIF-1α/Twist1/N-cadherin signaling pathway." (PMID 28430640, 2017). "During hypoxia, STAT3 and HIF-1α cooperatively activate HIF-1α target genes, VEGF, phosphoglycerate kinase 1 (PGK1), and carbonic anhydrase 9 (CA9) in prostate cancer cells." (PMID 28978186, 2017). "In pancreatic and prostate carcinomas, such complexes contain STAT3, HIF-1α, CREB-binding protein (CBP/p300), and redox effector factor-1/apurinic/apyrimidinic endonuclease (Ref-1/APE)." (PMID 28978186, 2017). "For instance, in prostate cancer cells, rapamycin decreases protein levels of HIF-1α by interfering with processes that promote HIF-1α protein stabilization." (PMID 29104248, 2017). "In the present study, the expression of HIF-1α was evaluated by immunohistochemistry in tissues of fetal prostates, normal prostates, intra-acinar of BPH, peri-acinar of BPH, prostate cancers and sarcomas of prostate." (PMID 26919249, 2016). "In human prostate cancer specimens, mPGES-1 was over-expressed in tumors with high Gleason score, elevated expression of VEGF and HIF-1α, high microvessel density and decreased expression of Dicer, miR15a and miR-186." (PMID 27322147, 2016). "With regard to prostate cancer, HIF-1α is overexpressed in actively growing prostate tissues: BPH and prostate cancer." (PMID 27975057, 2016). "Overexpression of miR-182 in prostate cancer cells led to a reduction of PHD2 and FIH1 expression and an increase in HIF1α level either under normoxic or hypoxic condition." (PMID 26205124, 2015). "Transfection of HIF1α-DM resulted in an accumulation of HIF1α in DU145 and PC-3 prostate cancer cells under normoxia." (PMID 26205124, 2015).